ICOS (inducible T cell costimulator)
Diseases named in the same sentence as ICOS in open-access papers (continued):
Sharing a sentence is not in itself a finding about the gene and the disease.
COVID-19 (26 papers, 2020 to 2024). A disease caused by infection with severe acute respiratory syndrome coronavirus 2. "Another potential explanation for the superiority of cTfh cells from severe COVID-19 patients is that the frequency of activated ICOS+ cTfh cells is higher in severe compared to mild patients." (PMID 37061513, 2023). "Total CD4+CXCR5+ Tfh cells and ICOS+Foxp3-activated Tfh cells increased and ICOS+Foxp3+ Tfr cells decreased in COVID-19 patients, especially in diabetic patients and those with severe disease." (PMID 35286241, 2022). "We observed subtle differences in induction of ICOS+CD38+ cTfh following vaccination based on prior history of COVID-19." (PMID 34874183, 2022). "Further, a NSCLC patient subgroup has normal lung tissue expressing high ACE2 and high ICOS transcripts, the latter potentially promoting a hyperimmune response, and possibly leading to severe COVID-19 pulmonary compromise." (PMID 36324736, 2022). "Tfh-ICOS signaling is critical for the generation of an anti-COVID-19 response; hospitalized COVID-19 patients exhibited B cells with a lower expression of ICOS-L, the ligand for ICOS on Tfh, when compared with ambulatory COVID-19 patients." (PMID 35493515, 2022). "COVID-19 patients also showed a decreased median proportion of early-activated Th1 (ICOS+/PD-1-): 0.3% (0.2–0.6) vs. 1.7% (0.7–2.1) (p < 0.001), Th2: 0.4% (0.2–0.8) vs. 2.81% (1.3–3.6) (p < 0.001) and Th17: 0.2% (0.1–0.4) vs. 1.2% (0.6–1.8) (p < 0.001)." (PMID 35203509, 2022). "Our early COVID-19 case study revealed that both ICOS+PD-1+CD4+ TFHs and activated CD38+HLA-DR+ CD4+/CD8+ T cells appeared transiently in patient's blood at 3 days prior to recovery, suggesting involvement of T cells in the resolution of COVID-19." (PMID 35004764, 2021). "In addition, ICOS signaling is impaired in COVID-19 patients requiring hospitalization." (PMID 34616619, 2021). "Indeed, we observed that the abundance of PD-1+ plasma cells was correlated with the numbers of ICOS+ PD-1+ Tfh, which could evidence that the COVID-19 recovered individuals still have a solid Tfh-B cell axis 10 months post-infection." (PMID 35069575, 2021). "This is in line with several studies trying to understand the immune profile of COVID-19 patients that report elevated frequencies of CD38+ ICOS+ CXCR5+ CD4+ T cells during acute disease." (PMID 37061513, 2023). "In contrast, both T cell populations in the paired COVID-19 dLNs showed classical activation markers, such as CD69, HLA-DR-DQ, ICOS and Ki67." (PMID 36774347, 2023). "We then compared CD3+ cells isolated from COVID-19-infected subjects vs. healthy controls and found increased expression of activation markers including CD69, CD83, ICOS, RGS1 as well as other stress related genes including HIF1A, ATF4, NFKB1, and PR1." (PMID 36881624, 2023). "Expression of PD1, ICOS, and CD38 were similar between COVID-19-naïve individuals with PAD syndromes and healthy donors at day 7 to 28 following vaccination, suggesting there was no defect in CD4+ T cell activation in most individuals with PAD syndromes." (PMID 36618402, 2022). "Despite the evaluated levels of circulating memory Tfh cells in both the lymph nodes and spleen of patients with COVID-19, Tfh cells with different phenotypes, CD4+ICOS+, CD4+ CXCR5+, and CD4+ Bcl-6+, were present at decreased levels." (PMID 34696395, 2021). "Total cTfh cell activation (PD-1+ICOS+) was similar between COVID-19 pregnant and nonpregnant women." (PMID 37036008, 2023). "In particular, the ICOS-ICOSL signaling in T helper cells, PKC signaling in T lymphocytes, T cell receptor signaling, calcium-induced T lymphocyte apoptosis, and CD28 signaling in T helper cells were all determined to be related to COVID-19 severity." (PMID 37308820, 2023). "Increased expression of CXCR5 and ICOS on SARS-CoV-2-specific CD4 T cells in mild to severe COVID-19 patients with acute infection has been reported, but none of the studies tested cTfh functionality directly." (PMID 37061513, 2023).
COVID-19 (continued). "A lower frequency of CD4+CXCR5+ICOS+ Foxp3+ Tfr cells was found in the diabetic patients compared to controls (p = .01) and non-diabetic COVID-19 patients (p = .02)." (PMID 35286241, 2022). "Furthermore, low frequencies of CD45RA-PD-1+CXCR5+cTfh cells were also observed, but elevated frequencies of activated cTfh (CD38+ICOS+) cells were positively correlated with anti-SARS-CoV-2 IgM and IgG titers in hospitalized COVID-19 patients." (PMID 34603308, 2021). "In particular, the expression of PD-1 and ICOS on CD4+ T cells and that of CD127 and CD40L on CD8+ T cells showed a marked decrease when the majority of blocking antibodies were added, both individually and as a pool, to PBMCs cultured with serum obtained from patients with COVID-19." (PMID 34784300, 2021). "However, upon considering a broader spectrum of TFH cells regardless of ICOS expression, CD4+, CXCR5+, and PD-1+ TFH were most abundant in COVID-19 patients with mild disease." (PMID 33361110, 2021).
rheumatoid arthritis (24 papers, 2013 to 2025). A chronic, systemic autoimmune disorder characterized by inflammation in the synovial membranes and articular surfaces. "Rheumatoid arthritis similarly showed increased usage of metallothionein, HLA, ICOS/CD38, TPH cells and other activation-associated cGEPs (Q < 0.05)." (PMID 40903640, 2025). "Fine-mapping and functional studies implicate rs117701653, a non-coding single nucleotide polymorphism in the CD28/CTLA4/ICOS locus, as a risk variant for rheumatoid arthritis and type 1 diabetes." (PMID 38459032, 2024). "Some ICOS-deficient patients develop autoimmune symptoms such as rheumatoid arthritis and autoimmune neutropenia, suggesting a potential role of ICOS in Treg/Tfr compartments." (PMID 36754569, 2023). "Some researchers observed that the frequency of CD4+CXCR5+ICOS^high Tfh cells increased significantly in the peripheral blood of rheumatoid arthritis patients compared with healthy controls." (PMID 40283219, 2025). "Higher ICOS expression is paralleled by an increase in circulating T peripheral helper (Tph) cells and, in rheumatoid arthritis patients, of blood and joint fluid Tph cells as well as circulating plasmablasts." (PMID 38459032, 2024). "ICOS has been found to be highly expressed on activated CD4+ T cells in patients with autoimmune conditions such as rheumatoid arthritis (RA), SLE, and inflammatory bowel disease." (PMID 24000287, 2013). "In contrast to PD-1/PD-L1 and CTLA-4, where agonistic approaches have therapeutic benefit, blockade of ICOS or its ligand (ICOSL) reduces disease severity in murine models of rheumatoid arthritis, such as the glucose-6-phosphate isomerase (GPI)-induced arthritis model." (PMID 41007749, 2025). "Different from SLOs, where Tfh cells orchestrate B cell responses and maturation, AP involves classical and non-classical Th1 cells highly expressing PD-1 and ICOS, similar to pathogenic T cell phenotypes in rheumatoid arthritis." (PMID 40107244, 2025). "Moreover, rheumatoid arthritis patients have higher levels of CD4+PD-1+CXCR5+ Tfh cells in peripheral blood than healthy controls, and the frequency of CD4+ICOS+CXCR5+ Tfh cells is linked with DBA/1 mice undergoing CIA." (PMID 34203838, 2021). "Furthermore, through abnormal regulation of Tfh cell function, ICOS is involved in the development and deterioration in some diseases like rheumatoid arthritis (RA), myasthenia gravis, and multiple sclerosis (MS)." (PMID 37325657, 2023). "Flow cytometry revealed T cell infiltration in the rheumatoid arthritis synovium with differential expression of PD-1, CD45RO, ICOS, TIGIT and CD38." (PMID 36270740, 2022). "Although there are currently no trials of therapy targeting CD40L or ICOS in SSc patients, a promising study in patients with rheumatoid arthritis using of an anti-CD40 antagonist Mab leads to a decrease in activated B-cells and autoantibody production." (PMID 34461933, 2021).
gastric cancer (21 papers, 2014 to 2025). A primary or metastatic malignant neoplasm involving the stomach. "For example, compared with early-stage gastric cancer, a higher proportion of Tregs express ICOS in advanced gastric cancer." (PMID 38556542, 2024). "In advanced gastric cancer, the proportion of ICOS in Tregs is highly expressed." (PMID 38506253, 2024). "ICOS+ Foxp3+ CD4+ T cells were abundantly observed in the late stages of gastric cancer." (PMID 35311157, 2022). "In addition, in gastric cancer, co-stimulation of ICOS and ICOSLG can lead to the activation of Tregs cells and may be associated with poor prognosis of patients." (PMID 37842091, 2023). "A number of T cell co-inhibitory molecules CTLA4, ICOS, CD274, PDCD1, and IDO were markedly downregulated by NPRL2 treatment which was in agreement with the data found in bioinformatics analysis in stomach cancer patients' samples." (PMID 39932765, 2025). "To understand the relationship of RORα and ILC2s-related markers and signature cytokines in patients with gastric cancer, we analyzed the correlation between RORα and T1/ST2, IL-17RB, CRTH2, ICOS, CD45, IL-13, and IL-5 in mRNA levels." (PMID 24741632, 2014). "The interaction of two molecules was also observed on tissue-derived transcript levels extracted from gastric cancer datasets TCGA and GSE62254, suggesting that ICOS and IDO1 may exert analogous functions in modulating tumor immune microenvironment (TIME)." (PMID 36077704, 2022). "The correlation between the mRNA levels of IL-13 and ICOS and CD45 was analyzed, respectively, and the results demonstrated that there was a positive correlation between IL-13 and ICOS and CD45 in patients with gastric cancer." (PMID 24741632, 2014). "Furthermore, there was a positive correlation between IL-13 and ICOS and CD45 in gastric cancer." (PMID 24741632, 2014).
glioma (17 papers, 2017 to 2026). A benign or malignant brain and spinal cord tumor that arises from glial cells (astrocytes, oligodendrocytes, ependymal cells). "Increased ICOS levels in patients demonstrate a correlation with greater glioma malignancy and a significant association with regulatory T cell (Treg) activity within the immune responses related to gliomas." (PMID 38275876, 2024). "These GSEA results further confirmed the profound association of ICOS with glioma-related immune response, consistent with what we observed in GO analysis." (PMID 36276141, 2022). "In conclusion, higher ICOS is correlated with more malignancy of gliomas and is significantly associated with Treg activity among glioma-related immune responses." (PMID 36276141, 2022). "Given the profound associations with distinct genomic alterations, ICOS is supposed to play a vital role in gliomagenesis, glioma progression, microenvironment remodeling, and drug resistance, further confirming its robust correlation with higher malignancy of gliomas." (PMID 36276141, 2022). "In the analysis of cell lineage, gliomas with elevated ICOS levels exhibited a tendency to recruit dendritic cells, monocytes, and macrophages into the TME." (PMID 38275876, 2024). "It turned out that ICOS was mainly expressed and activated on Tregs, which further validated the immunosuppressive feature of ICOS among gliomas." (PMID 36276141, 2022). "ICOS showed a strong correlation with these molecules, providing more evidence for immunotherapy combination for gliomas." (PMID 36276141, 2022). "To confirm that ICOS expression was also upregulated at the protein level, we performed IHC staining for ICOS on a glioma TMA." (PMID 36276141, 2022). "Our study would be the first comprehensive report to demonstrate the molecular and clinical characterization of ICOS expression among pan-gliomas." (PMID 36276141, 2022). "Overall, these results indicated that gliomas with higher ICOS tended to recruit multiple infiltrating immune cells into the tumor and were more associated with Tregs in more malignant gliomas." (PMID 36276141, 2022). "In conclusion, our study reveals the potential of therapies targeting ICOS for glioma immunotherapy." (PMID 36276141, 2022). "Functional enrichment analyses revealed that ICOS was mainly involved in glioma-related immune response." (PMID 36276141, 2022). "Our study, mainly focusing on transcriptome characterization and clinical significance, extended the research in whole grades of glioma, further highlighted the essential role of ICOS among pan-gliomas, and profoundly expanded the spectrum of research on ICOS." (PMID 36276141, 2022). "ICOS expression showed a positive correlation with the immune score, stromal score, and microenvironment score, and Higher-ICOS gliomas tended to recruit multiple infiltrating immune cell types." (PMID 36276141, 2022). "Our study provides the most comprehensive investigation of the expression profile of ICOS in whole WHO grade gliomas, together with its related molecular signature, clinical significance, and prognostic value." (PMID 36276141, 2022). "ICOS was significantly upregulated in the mesenchymal than that in other subtypes, suggesting the potential discriminatory power of ICOS for mesenchymal-subtype gliomas." (PMID 36276141, 2022). "In our study, we found that CTLA-4 was significantly correlated with PD-1, CD40, and ICOS in patients with glioma and glioblastoma." (PMID 31911758, 2020). "To understand the relevance of ICOS and PD-1 expression in brain TILs, we treated 8 glioma-bearing mice with Delta24-RGD and harvested the brains and spleens on day 14 after therapy." (PMID 32642679, 2020). "Furthermore, we found that 5 immune inhibitors (KDR, TIGIT, VTCN1, LAG3 and ADORA2A) and 2 immune stimulators (ICOS and TNFRSF25) were significantly associated with HIC2 in gliomas." (PMID 36650953, 2023).
glioma (continued). "For the LGG cohort, Circos plots showed that ICOS level was positively correlated with all of these immune checkpoints among three datasets, exhibiting synergistic interactions of these immune checkpoints in gliomas." (PMID 36276141, 2022). "To elucidate the ICOS expression profile and clinical characterization in all gliomas, we collected microarray data of 301 glioma samples from the Chinese Glioma Genome Atlas (CGGA) dataset (CGGA301) and performed this integrative analysis of ICOS among whole-grade gliomas." (PMID 36276141, 2022). "Our study highlights the role of ICOS in glioma and may facilitate therapeutic strategies targeting ICOS for glioma." (PMID 36276141, 2022). "This study investigated the transcriptome profile and clinical characterization of ICOS in gliomas." (PMID 36276141, 2022). "Overall, the IHC staining intensity of ICOS was low-moderate in glioma tissues." (PMID 36276141, 2022). "Kaplan–Meier curves were delineated to explore the prognostic role of ICOS in gliomas." (PMID 36276141, 2022). "Although the exact mechanisms of ICOS in the regulation of tumorigenesis and development of glioma are not well understood, some T-cell subpopulations might play essential roles in this process." (PMID 36276141, 2022). "Furthermore, based on seven clusters of metagenes, GSVA identified that ICOS was tightly associated with HCK, LCK, MHC-I, MHC-II, STAT1, and interferon, especially with LCK, suggesting a strong correlation between ICOS and T-cell activity in gliomas." (PMID 36276141, 2022). "We believe that ICOS will become a potential hotspot for glioma immunotherapy." (PMID 36276141, 2022). "The expression of ICOS, TNFSF14, and ULBP1 was assessed by immunohistochemistry in patients with glioma, confirming that TNFSF14 was associated with the clinical outcome of patients with glioma." (PMID 31451090, 2019). "Thus, considering the remarkable immunosuppressive effect of ICOS, an anti-ICOS antagonist might be more appropriate in glioma; however, this requires a further in-depth understanding of the mechanism of ICOS." (PMID 36276141, 2022). "Moreover, IDH wild-type gliomas were found to be associated with a higher ICOS expression pattern compared to IDH-mutant counterparts in three datasets, which further confirmed the correlation between ICOS and the aggressiveness in gliomas." (PMID 36276141, 2022). "Studies have shown that the immune checkpoint ligands ICOS, BTLA, TNFRSF1A, and TNFRSF1B all contribute to glioma immune evasion." (PMID 36882457, 2023). "We found that ICOS was significantly upregulated in higher-grade, IDH wild type, and mesenchymal subtype of gliomas." (PMID 36276141, 2022). "Moreover, ICOS could contribute as an independent prognostic factor for gliomas." (PMID 36276141, 2022). "In addition, our Circos plots also demonstrated the robust interaction between ICOS and ICOSLG in both LGG and GBM, further confirming the pro-oncogenic role of the ICOS/ICOSLG pathway in gliomas." (PMID 36276141, 2022). "In GBM, on the one hand, the correlation between ICOS and CD8+ T cells was enhanced, and on the other hand, the correlation with Tregs was synchronously increased, suggesting the dualistic role of ICOS in gliomas." (PMID 36276141, 2022). "Indeed, it has recently been shown that glioma-infiltrating Tregs expressed PD1, ICOS, and Tim-3, and that PD1-expressing Tregs were impaired in their suppressive activity." (PMID 32117743, 2020).